CDH1 (cadherin 1)
Diseases named in the same sentence as CDH1 in open-access papers (continued):
Sharing a sentence is not in itself a finding about the gene and the disease.
cancer (continued). "In addition, Remodelin was shown to weaken doxorubicin resistance and suppress hypoxia in cancer through NAT10/(VIM/TWIST/CDH1) and NAT10/(HIF1A/HIF2A) respectively." (PMID 33723305, 2021). "In this special group of families that have the germline mutation for CDH1 but do not meet the clinical criteria, the evolution seems to be different from the classic families, with lower risk of cancer and onset of the disease at a higher middle age." (PMID 34008707, 2021). "We then checked the expression of the canonical cell-type markers: cancer/epithelial cell marker genes (Cdh1, Krt18, and Krt5); mesenchymal cell marker genes (Col1a1, Col1a2, and Col3a1); immune cell marker genes (Ptprc, Cd68, and Csf1r); and endothelial cell marker genes (Pecam1, Emcn, and Cdh5)." (PMID 34497807, 2021). "In addition, we found that EED, a core component of PRC2, and JARID2, an accessary factor of PRC2, were essential for TGF-β-induced EMT through CDH1 repression in cancer cells." (PMID 33779563, 2021). "The differential inhibition between wild-type and CDH1-null cells was frequently statistically significant at sub-micromolar concentrations and consistent with the effective concentrations observed in numerous cancer cell lines." (PMID 35008338, 2021). "In order to further understand the clinical significance of MAL2, we selected the top three hub genes (MAL2, CDH1, and TPD52) from the GGI network to analyze their potential roles in drug susceptibility in OC according to the Cancer Therapeutics Response Portal (CTRP)." (PMID 35111745, 2021). "Further, our co-expression analysis also showed that key EMT-related factors such as MMP2, MMP9, CDH2, TGFB1, and VIM were highly expressed when CHN1 was highly expressed, while CDH1 was expressed at lower levels, suggestive of a potential cancer-promoting function of CHN1." (PMID 34152250, 2021). "In addition, because E-cadherin (CDH1) expression tends to be significantly reduced in cancer cells, we also included detection of its mRNA expression levels." (PMID 34124226, 2021). "Moreover, CDH1 and FOXA2 are linked to each other in carcinoma progression, evidenced by the loss of silencing FOXA2 leading to E-cadherin downregulation, EMT and metastasis." (PMID 34827193, 2021). "CDH1 positive patients undergo routine endoscopies and biopsies are taken to study the gastric tissue and if the biopsy demonstrates signet ring cell changes or in situ carcinoma, they are advised for prophylactic gastrectomy." (PMID 33062523, 2020). "The complicated relationship between CDH1 and cancer progression was described when suppression of CDH1 in B cell acute leukemia initially resulted in mitotic catastrophe and apoptosis, but long-term CDH1 loss contributed to development of treatment resistance." (PMID 32805721, 2020). "Therefore, CDH1 inactivation is related with multifocal cancer and the propensity of bilateral cancer." (PMID 33204419, 2020). "Downregulation or inactivation of the CDH1 gene is involved in cancer progression and metastasis." (PMID 33240310, 2020). "Another known cancer gene present in this subnetwork is CDH1." (PMID 32471470, 2020). "To further study the participation of P2X7R in the epithelial-to-mesenchymal transition (EMT), we assessed the effect of stimulating 4T1 cancer cells with BzATP on the expression of genes associated with the mesenchymal (SNAI1, ZEB1, TWIST) or the epithelial (ZO1, CDH1) phenotypes." (PMID 32825056, 2020). "Moreover, the correlation between PAH and Cdh1 in cancer progression and its potential application in cancer therapy should be performed in the future to elucidate its molecular mechanism during the progression of HCC." (PMID 33260674, 2020). "We previously discovered that TS expression is correlated with the EMT phenotype in the NCI-60 transcriptomic database by using a pan-cancer EMT gene ratio (Vimentin/E-Cadherin, VIM/CDH1), but the mechanistic involvement of the TS enzymatic activity on EMT/CSCs has never been shown." (PMID 30737477, 2019).
cancer (continued). "CDH1 and SPDEF are closely associated with cancer cell metastasis." (PMID 30977227, 2019). "There are clear examples with germline mutations in genes like adenomatous polyposis coli (APC), cadherin 1 (CDH1), BRCA1, von Hippel-Lindau tumor suppressor (VHL), and ataxia telangiectasia mutated (ATM) which are causative for the development of cancer in specific types of tissue." (PMID 31001323, 2019). "Interestingly, CDH1 has also been established as a direct target of miR-9-5p in a multitude of human cancers." (PMID 31888045, 2019). "Previous studies have explored the role of known cancer predisposition genes in individuals with hereditary diffuse gastric cancer who do not have known CDH1 mutations." (PMID 29706558, 2018). "This is an interesting finding because the E-cadherin (CDH1) expression in cancer cells exposed to r-μg is an unknown area." (PMID 30545079, 2018). "It was also revealed that many cancer cell lines lack the ability to activate APCCdh1 when under replication stress, and that CDH1-depleted cells undergo senescence in G2, suggesting that APCCdh1 may normally act as a barrier to genome instability." (PMID 29954095, 2018). "Van der Post et al6 reviewed the gastric specimens of 103 HDGC families without CDH1 mutations, and although advanced cancers showed similar morphology to that of mutation carriers, in situ SRCC and pagetoid spread of signet ring cells were not present." (PMID 28688938, 2018). "In addition to CDH1, the gene encoding E-cadherin, germline pathogenic variants in PALB2 and other cancer-predisposing genes have been identified by whole-exome sequencing of HDGC families." (PMID 30568591, 2018). "Loss of expression of E-cadherin (CDH1), and induction of expression of N- or R-cadherin (CDH2 or CDH4), triggers a series of events that allows cancer cells to become less dependent of their micro-environment, thereby promoting cell migration, invasion and metastasis." (PMID 29164272, 2018). "In a recent study, we suggest that polymorphic variants in AXIN2 and CDH1 may be associated with NSCL/P susceptibility, and reinforce the putative link between cancer and oral clefts." (PMID 29274157, 2018). "Furthermore, the cross-talk between MSCs and cancer cells relates to CDH1 (E-cadherin) and IL-1B levels." (PMID 29760166, 2018). "A palliative paracentesis was performed; cytological conformation of cancer cells was confirmed and used to establish the c.1380delA CDH1 SB.mhdgc-1 cancer cell line.c.1380delA CDH1 SB.mhdgc-1 grow as a pleiomorphic, irregular shaped cells monolayers to near confluency." (PMID 28460635, 2017). "Interestingly, recent studies have demonstrated a relationship between congenital malformations and malignancies, and genetic alterations in AXIN2 and CDH1 are associated with both NSCL ± P and cancer of breast and gastric." (PMID 28376813, 2017). "In sum, the findings of this retrospective polyps study combined with the novel CDH1 and NRAS germline mutations found in the CRC groups emphasize the existence of the Taiwanese-specific genome and provided candidate genes for cancer risk assessment in the general population." (PMID 29069792, 2017). "The results suggest that polymorphic variants in AXIN2 and CDH1 may be associated with NSCL ± P susceptibility, and reinforce the putative link between cancer and oral clefts." (PMID 28376813, 2017). "CDH1 is an original cadherin and plays a pivotal role in epithelial structure remodeling and maintaining the stemness of stem cells in breast epithelial and cancer cells." (PMID 28392805, 2017).
cancer (continued). "The physiological role of Cdh1 has been extensively studied in the context of human cancer, since downregulation of Cdh1 has been reported in many cancers, including those of prostate, ovary, liver, brain, and during the malignant progression of a B-lymphoma cell line." (PMID 28049433, 2017). "However, only one gene CDH1 has been considered previously as cancer gene in Sanger Institute Cancer Gene Census." (PMID 28198667, 2017). "We hypothesize that if mutations in genes related to EMT, such as CDH1 or CTNNB1, cause a substantial number of cancer cells to detach from a primary tumor, many or most patients with regional or distant disease would have mutations in EMT genes." (PMID 29156750, 2017). "Since all the tumors were carcinomas, it is reasonable to think that reduced CDH1 expression played a role in detachment of cancer cells for patients diagnosed with regional or distant disease, given that CDH1 is an important epithelial cell-cell adhesion molecule." (PMID 29156750, 2017). "We found that, for each gene, over 95% of primary carcinomas across anatomic sites had no CDH1 or CTNNB1 mutations, as well as low prevalences of carcinomas with at least one mutation for the large majority of individual sites." (PMID 29156750, 2017). "Apart from these 5 patients, only one patient (Sample ID 1705) developed cancer with only one heterozygous germline CDH1 mutation with the absence of other somatic mutations." (PMID 27121310, 2016). "These factors may repress the gene transcription by binding to the promoter region of genes involved in cell-cell adhesion such as E-cadherin (CDH1), and allow dissociation of cancer cells from the epithelial matrix." (PMID 27654478, 2016). "Decreased expression of CDH1 and subsequent nuclear translocation of β-catenin compromised cellular adhesion and increased cellular invasive and metastatic potential in several types of cancers." (PMID 27801803, 2016). "In addition, EZH2 promotes epithelial-mesenchymal transition (EMT), a process that is associated with cancer progression and metastasis, by interacting with transcription factor SNAIL1 and suppressing expression of epithelial marker E-cadherin (CDH1)." (PMID 26683709, 2016). "Our data suggested co-expression of CDH1 and CTNNB1 in the cell membrane might be needed for cell stability because cell instability often causes malignant change of the cancer cell." (PMID 27600761, 2016). "The suppression of Suv39H1 could be a good therapeutic approach to rescue CDH1 expression in cancers where the DNA methylation levels are high, such as in BLBC." (PMID 26905733, 2016). "Importantly, depletion of endogenous Cdh1 in these cancer cell lines significantly suppressed the protein levels of WWP2 but not other NEDD4 family proteins examined." (PMID 27462441, 2016). "As elevation of Cdk activity has been found in most cancer cells, Cdh1 might largely exist in an APC-free population in these cancer cells, which directly interacts with WWP2 to facilitate its auto-inhibition." (PMID 27462441, 2016). "Moreover, the absence of CDH1 gene expression in cancer can also imply that repression of CDH1 in cancer may be caused by other mechanisms such as C/A single nucleotide polymorphism at the promoter of CDH1 or due to CDH1 promoter hyper methylation, in which both can suppress CDH1 expression." (PMID 27601996, 2016). "Indeed proteolysis of Cdh1 mediated by the ubiquitin-ligase SCF has been described in human cancer cell lines." (PMID 27374082, 2016). "Therapeutically, the increased levels of replication stress in cancer cells with inactivated Cdh1 may create sensitivity to targeted agents that target the replication checkpoint, such as inhibitors of Wee1, ATR or Chk1." (PMID 26650195, 2016). "LOXL2 induces EMT by stabilizing Snail, a suppressor of CDH1 in carcinoma progression." (PMID 27285767, 2016). "In the presence of EBV, CDH1 methylation was present in 27.8% (5/18) of cancer samples." (PMID 26032781, 2015).
cancer (continued). "CDH-1 mRNA expression was higher in benign compared to malignant neoplasms and normal mammary tissue and thus may serve as a prognostic marker." (PMID 26370564, 2015). "Despite this, our data revealed that the association between CDH1 methylation and cancer was not significant (p = 0.241)." (PMID 26032781, 2015). "Because of the striking differences in mRNA signals in cancerous and noncancerous cells, we next asked whether this influences overall mRNA levels of CDH1 and HIF1α in tissue sections representing cancer and cancer-free areas." (PMID 26029826, 2015). "Interestingly, we found increased CDH-1 gene expression in benign compared to malignant neoplasms, which supports the role of CDH-1 as a marker for cell differentiation." (PMID 26370564, 2015). "We propose a working hypothesis in which MSCs interact with cancer cells and the outcome of this dynamic interaction is dependent on the expression of CDH1/IL-1β by cancer cells." (PMID 26204886, 2015). "The cells in which CDH1 expression is inhibited can present properties of cancer stem cells." (PMID 24387758, 2014). "However, when cancer cells lose differentiation status, regulation of CDH1 can be disrupted resulting in cytosolic and nuclear expression patterns." (PMID 24586868, 2014). "Moreover, we also examined the effects of JARID2 knockdown in the status of histone H3 methylation and EZH2 recruitment on the regulatory regions of CDH1 and miR-200 family genes in another cancer cell line, HT29." (PMID 25542019, 2014). "However, the frequency of CDH1 methylation in cancer lesion was significantly lower than that in non cancerous mucosa in the subjects with GC, although the frequency of DAPK methylation was not." (PMID 23280118, 2013). "Analyses of primary cancers and cancer cell lines from different entities revealed an inverse relationship of ZEB1 and E-cadherin (encoded by the CDH1 gene) expression and a positive correlation between ZEB1 and N-cadherin (encoded by the CDH2 gene) expression." (PMID 23667256, 2013). "However, recent data demonstrate that CDH1 somatic alterations (such alterations accumulate in the cancer cells of the body over a person's lifespan) are as frequent in intestinal as in diffuse GC, suggesting an important role of CDH1 in both the histotypes." (PMID 24204729, 2013). "However, although CDH1 is silenced in some cancer cell lines by PRC2, it is still expressed by parental DU145 cells." (PMID 21501485, 2011). "In contrast to the frequency of Skp2 overexpression, loss of Cdh1 is not a frequent event in human cancer." (PMID 19549334, 2009). "It appears likely that, in many instances, CDH1 variants will require the presence of other etiologic factors to increase disease risk, as E-cadherin deficiency is usually associated with cancer progression rather than initiation." (PMID 18482459, 2008). "Third, external validation using Cancer Dependency Map RNA-sequencing (1699 cell lines) demonstrated that texture discrimination (16.8-fold) corresponded quantitatively to independent molecular differences (14.6-fold VIM/CDH1 ratio), achieving concordance within 15%." (PMID 42106500, 2026). "Underlying these processes, cancer cells overexpressing FSTL3 exhibited increased expression of the genes associated with epithelial-mesenchymal transition (Vim, Zeb-1, Snai1/2) and extracellular matrix organization (Ecm1), while expression of epithelial markers (Epcam, Cdh1) decreased." (PMID 41029436, 2025). "Surveillance strategies for individuals with identified CDH1 mutations typically involve regular upper gastrointestinal endoscopies (EGD) starting at an early age, although the efficacy of such surveillance remains debated due to the often normal findings in patients who later develop cancer." (PMID 40585607, 2025).
cancer (continued). "Although proline-directed phosphorylation of CDH1 modulates its E3 ligase activity, it remains unknown whether its activity is subject to further regulation after phosphorylation and how to harness this E3 ligase for cancer therapy." (PMID 38622115, 2024). "In many cancers, the loss of E-cadherin is attributed to transcription factors such as SNAIL, SLUG, TWIST, ZEB1, and ZEB2, which bind to E-box sequences in the promoter region of the CDH1 gene and negatively regulate its expression, often through promoter methylation." (PMID 39728992, 2024). "Interestingly, yarrow-Sep inhibited key lipid metabolic targets in CRC cells extensively shown to be implicated in cancer dissemination and prognosis —SREBF1, FASN, ABCA1 and HMGCR— and epithelial to mesenchymal targets—CDH1, ATP1B1, CDH2 and Vimentin—augmenting cell adhesion." (PMID 38576446, 2024). "Hence, depending on which SOX factors are expressed in cancer cells, they may have an activating or inhibitory effect on CDH1 expression." (PMID 38675711, 2024). "Furthermore, deficiency of CDH1 maybe oncogenic for cancer initiation and over expression of CDH1 mutants could advance cancer progression by inhibiting NK cells and T cells." (PMID 38241355, 2024). "Cancer cells undergoing the EMT process through overactivation of TGFβ signaling exhibit sustained hypermethylation of promoters and subsequent loss of expression in downstream cell-junction-related effector genes, including cadherin 1 (CDH1) and claudin 6 (CLDN6)." (PMID 37566041, 2023). "Notably, interference of CDH1, also an inhibitor of cancer, may be involved in the cancer inhibitory effect of CTNNA1." (PMID 36741258, 2023). "For example, Entinostat, a histone deacetylase inhibitor, may be able to reduce cancer risk by both promoting apoptosis in established CDH1-null foci and restore expression of the non-mutant copy of CDH1 in gastric organoids." (PMID 36869400, 2023). "In this syndrome, germline mutations of the E-cadherin gene (CDH1) are causative events and, at the time of clinical diagnosis, mutation carriers frequently display advanced disease stages with diffuse invasion of the gastric wall and cancer spreading into the peritoneal cavity and adjacent organs." (PMID 37938268, 2023). "Despite this categorization, a thorough evaluation of families with germline CDH1 pathogenic or likely pathogenic (P/LP) variants has indicated that HLBC is unlikely to comprise a distinct cancer syndrome but rather is part of the greater spectrum of diseases associated with CDH1 mutations." (PMID 37758801, 2023). "Notably, CDH1 became de-methylated and selectively re-expressed in cancer cell lines upon treatment with a histone deacetylation inhibitor named trichostatin, raising the possibility that such an approach may have therapeutic benefit in HDGC." (PMID 36869400, 2023). "Approximately one third of patients with a CDH1 pathogenic variant will never develop symptomatic cancer and therefore a careful watch and wait strategy is a reasonable option in some individuals especially given the profound impact of a total gastrectomy on the quality of life." (PMID 37221458, 2023). "Moreover, the CDH1 gene has been reported to exhibit promotor methylation in 43% of HNSCC cancers." (PMID 36072342, 2022).